LOX (lysyl oxidase)
Diseases named in the same sentence as LOX in open-access papers (continued):
Sharing a sentence is not in itself a finding about the gene and the disease.
rheumatoid arthritis (4 papers, 2014 to 2020). A chronic, systemic autoimmune disorder characterized by inflammation in the synovial membranes and articular surfaces. "Another of our previous studies, on rheumatoid arthritis, found that inhibition of LOX expression in rat synovial fluid can downregulate MMP-2 and MMP-9 expression." (PMID 31777578, 2019). "Additionally, our previous study on rheumatoid arthritis also found that LOX expression levels in synovial fluid were positively correlated with the expression levels of MMP-2 and MMP-9." (PMID 31777578, 2019).
Stroke (4 papers, 2018 to 2021). Sudden impairment of blood flow to a part of the brain due to occlusion or rupture of an artery to the brain. "These loci provide insights into lacunar stroke pathogenesis, highlighting disruption of the vascular extracellular matrix (COL4A2, LOX, SH3PXD2A, GPR126, HTRA1), pericyte differentiation (FOXF2, GPR126), TGF-β signalling (HTRA1), and myelination (ULK4, GPR126) in disease risk." (PMID 33773637, 2021).
Alzheimer disease (3 papers, 2019 to 2023). A progressive, neurodegenerative disease characterized by loss of function and death of nerve cells in several areas of the brain leading to loss of cognitive function such as memory and language. "For example, diminished LOX activity is found in certain connective tissue disorders and LOX is increased in liver cirrhosis and Alzheimer's disease." (PMID 29065711, 2019).
aortic stenosis (3 papers, 2017 to 2024). Aortic valve stenosis is a aortic valve disease caused by the incomplete opening of the aortic valve. "In patients with severe aortic stenosis (AS) and HF, cardiac and circulating miR-19b levels were inversely correlated with LOX protein levels, CCL and LV stiffness." (PMID 31766500, 2019).
colitis (3 papers, 2018 to 2023). Inflammation of the colon. "Moreover, Lox and Loxl1 lysyl oxidase encoding genes showed elevated expression levels in S4 cells from DSS-treated mice and the blockade of these enzymes efficiently reduced the severity of DSS colitis." (PMID 35563571, 2022). "Other oxylipin species, produced via the LOX and COX pathway, can also modulate DSS‐induced colitis." (PMID 36795015, 2023).
diabetic retinopathy (3 papers, 2019 to 2025). "This section focusses on diabetic retinopathy and two additional prominent ocular diseases associated with abnormal LOX family and LOX-PP activities." (PMID 35563478, 2022). "In addition, LOX is known to be upregulated in diabetic retinopathy, which is a disease also associated with increased ECM crosslinking and resultant BrM thickening." (PMID 40498044, 2025). "Moreover, it provides a basis for further investigation to determine if inhibiting LOX overexpression may be a useful strategy for preventing retinal vascular lesions associated with the pathogenesis of diabetic retinopathy." (PMID 31546618, 2019). "Findings from the current study highlight the relevance of LOX upregulation in human diabetic retinopathy." (PMID 31546618, 2019). "The functionality of the thickened BM is compromised by high glucose (HG)-induced LOX upregulation and increased activity, which leads to breakdown of blood-retinal-barrier (BRB) characteristics associated with diabetic retinopathy." (PMID 31546618, 2019). "Similarly, in diabetic retinopathy, LOX overexpression, activity, and elevated LOX propeptide have been documented." (PMID 35563478, 2022). "Further studies are needed to determine if vitreous sampling for LOX could be useful as a biomarker and aide in identifying progression of diabetic retinopathy status." (PMID 31546618, 2019). "In this review we will focus on findings specifically regarding the properties and mechanisms of pro-LOX processing and LOX-PP in the context of ECM modulation, cancers, and diabetic retinopathy." (PMID 35563478, 2022). "Hence, in this study, we investigated whether patients with advanced diabetic retinopathy expressed altered levels of LOX in the vitreous humor, compared to those of non-diabetic subjects." (PMID 31546618, 2019).
dissection (3 papers, 2016 to 2020). The separation and isolation of tissues for surgical purposes, or for the analysis or study of their structures. "Louis, MO), a LOX inhibitor, was used to build the model of aortic dissection in mice." (PMID 27608489, 2016).
esophageal cancer (3 papers, 2021 to 2025). A primary or metastatic malignant neoplasm involving the esophagus. "The top GPR176-correlated genes (PDPH, KIREL1, CLEC12A-AS1, CERCAM, IKBIP, LOX, COL5A2 and ELF3) were more highly expressed in oesophageal cancer than in normal tissue (p < 0.05), but the converse was true for C9orf152 and MT-TP (p < 0.05)." (PMID 37584712, 2023).
fungal infection (3 papers, 2015 to 2024). "During co-application with fungal infection, the pathogen itself had only a small effect on all the gene expressions tested except in LOX gene expression." (PMID 31120923, 2019). "In relation to this, we also proved in this study that 13-HODE, a LOX-oxylipin, decreases significantly during the growing season, i.e. with the increase of fungal infection and fumonisin production." (PMID 26378580, 2015). "In P. radiata, only the relative expression of LOX, ASR, SN and CkZb increased due to fungal infection." (PMID 39080528, 2024).
gastric ulcer (3 papers, 2012 to 2024). An ulcerated lesion in the mucosal surface of the stomach. "Current research suggests that Citronellol might prevent gastric ulcer caused by NSAIDs (Indomethacin) by interfering with the COX and LOX pathways, which are linked to oxidative stress, inflammation, and ulcerative potential." (PMID 39342545, 2024).
Hypercholesterolemia (3 papers, 2019 to 2024). An increased concentration of cholesterol in the blood. "However, in the porcine model fed a high-fat diet (HFD) we observed that hypercholesterolemia downregulated aortic LOX expression in the earliest stages of the atherosclerotic process (fatty streaks in the aorta after 100 days of diet intervention)." (PMID 31615160, 2019). "Interestingly, statins, lipid-lowering drugs widely used in the management of vascular diseases that improve endothelial function, normalize vascular LOX down-regulation induced by TNFα in vitro and by hypercholesterolaemia in vivo." (PMID 31615160, 2019). "Our study, therefore, examined the direct contribution of LOX activity to arterial wall stiffening induced by chronic d-flow without confounding effects of hypercholesterolemia or ApoE inactivation." (PMID 39143955, 2024).
hyperlipidemia (3 papers, 2021 to 2024). "Additionally, abnormal LOX metabolism maybe connected to the growth of many metabolic diseases, including fatty liver, IR, and hyperlipidemia." (PMID 38345057, 2024).
intracranial aneurysm (3 papers, 2021 to 2025). "Atherosclerotic lesions contain pathological levels of LOX, and loss of LOX is associated with intracranial aneurysm rupture." (PMID 40465757, 2025).
invasive breast carcinoma (3 papers, 2009 to 2021). A carcinoma that infiltrates the breast parenchyma. "In blood vessels LOX is expressed both the endothelium and the vascular smooth muscle cells; LOX expression is also upregulated in invasive breast cancer cells." (PMID 19440335, 2009).
ischemic stroke (3 papers, 2015 to 2022). A stroke disorder caused by obstruction of blood flow to the brain, due to thrombotic (local blood clot formation) or embolic (due to a blood clot or other material traveling from another site) event. "Another Japanese community‐cohort study showed that sLOX‐1 levels have been used in a formula to calculate LOX index and this LOX index can predict ischemic stroke during follow‐up." (PMID 35909324, 2022).
lymphoma (3 papers, 2022 to 2024). A malignant (clonal) proliferation of B- lymphocytes or T- lymphocytes which involves the lymph nodes, bone marrow and/or extranodal sites. "The contribution of Reed–Sternberg-derived LOX seems to be marginal, possibly due to the low number of these cells in definite lymphoma areas, as their distribution is generally scattered, rather than concentrated in aggregates." (PMID 35008423, 2022). "The reported evidence of gene expression signatures related to the ECM in lymphomas, together with our data on the overexpression of LOX in HL, can extend this therapeutic approach to hematologic neoplasia." (PMID 35008423, 2022). "Based on these data, digital pathology may help in the staging of lymphomas, and lysyl oxidase may represent a target for therapy in Hodgkin lymphomas." (PMID 35008423, 2022). "Moreover, not all lymphoma cells in HL are Reed–Sternberg, as documented by the IHC showing double staining for CD30/LOX or MUM-1/LOX." (PMID 35008423, 2022).
Menkes disease (3 papers, 2016 to 2024). A usually severe multisystemic disorder of copper metabolism, characterized by progressive neurodegeneration and marked connective tissue anomalies as well as typical sparse abnormal steely hair. "A mutation in the ATP7A gene is the cause of Menkes disease, it prevents the supply of copper ions to enzymes dependent on them, such as dopamine β-hydroxylase and lysyl oxidase." (PMID 38248841, 2024).
mesothelioma (3 papers, 2020 to 2022). A usually malignant and aggressive neoplasm of the mesothelium which is often associated with exposure to asbestos. "There is a strong rationale for lysyl oxidase inhibitors as a therapeutic approach in mesothelioma due to their ant-fibrotic mechanisms, synergism with chemotherapies, and modulation of EMT in mesothelioma." (PMID 35205728, 2022). "We have presented evidence that lysyl oxidase expression and activity are significantly dysregulated in mesothelioma." (PMID 35205728, 2022). "Overall, the evidence suggests that LOX/LOXLs are upregulated within mesothelioma patients, play a role in the pathogenesis of MPM and are potential therapeutic targets." (PMID 35205728, 2022). "Coupled with lysyl oxidase inhibitors’ anti-fibrotic activity and possible regulation of immune cell infiltration, their combination has potential as a treatment option for mesothelioma." (PMID 35205728, 2022). "It is anticipated that lysyl oxidase inhibitors could alleviate mesothelioma patients’ fibrotic response to chemotherapies, increase immune infiltration, extend survival and increase the quality of life." (PMID 35205728, 2022). "Upregulation of LOX/LOXL is common in cancers and fibrotic diseases, whereas in rare cancers such as mesothelioma comparatively little is known." (PMID 35205728, 2022). "However, four (LOX, LOXL1, LOXL2, LOXL4) and three (LOX, LOXL1, LOXL4) members were present in the mesothelioma (MESO; 87 patients, 239 genes) and ovarian serous cystadenocarcinoma (OV; 427 patients, 209 genes) datasets." (PMID 33383846, 2020). "However, little is known about LOX and LOXL family involvement in mesothelioma." (PMID 31921422, 2020).
myeloproliferative neoplasm (3 papers, 2020 to 2025). A clonal hematopoietic stem cell disorder, characterized by proliferation in the bone marrow of one or more of the myeloid (i.e., granulocytic, erythroid, megakaryocytic, and mast cell) lineages. "Lysyl oxidase has been shown to be elevated in patients with certain malignancies, including myeloproliferative neoplasms, which are associated with increased thrombotic risk." (PMID 34988471, 2021). "In myeloproliferative neoplasms, platelets have been shown to express lysyl oxidase, and increased lysyl oxidase activity is associated with increased platelet adhesion to collagen and increased arterial thrombus formation in a mouse model." (PMID 34988471, 2021). "In preclinical studies, inhibition of lysyl oxidase has been shown to attenuate progression of myelofibrosis, a myeloproliferative neoplasm, and triple-negative breast cancer and thus is a promising novel therapy." (PMID 34988471, 2021).
neuroblastoma (3 papers, 2016 to 2025). Neuroblastoma (NB) is the most common solid, extracranial childhood tumor. "SH-SY5Y neuroblastoma cytotoxicity at low concentrations was positively related with lipophilicity parameters and LOX allosteric docking affinity." (PMID 40427448, 2025). "At the transcript level, the pattern of LOX/LOXL expression observed was very similar among the pericyte samples, the exception being the neuroblastoma-derived pericytes in which LOXL1 was more highly expressed than the other family members." (PMID 28553358, 2017). "A similar LOX/LOXL expression pattern was detected in the pericyte sample derived from ependymoma, but not in the other pericyte sample derived from neuroblastoma." (PMID 28553358, 2017).
occipital horn syndrome (3 papers, 2015 to 2021). Occipital horn syndrome (OHS) is a mild form of Menkes disease (MD), a syndrome characterized by progressive neurodegeneration and connective tissue disorders due to a copper transport defect. "Reduced activity of LOX is also implicated in abnormal vasculopathy such as the vascular tortuosity and peripheral aneurysms in MD and its allelic variant, occipital horn syndrome (OHS)." (PMID 26347346, 2015). "Other than cancer, lysyl oxidase activity is also found reduced in nutritional copper deficiency and lathyrism and in two X-linked recessively inherited disorders, Menkes disease, and occipital horn syndrome (OHS)." (PMID 32542505, 2020).
rectal cancer (3 papers, 2016 to 2025). A primary or metastatic malignant neoplasm that affects the rectum. "Results indicated that the LOX G473A variant-positive population displayed an enhanced susceptibility to lung, colorectal, colon, and rectum cancers." (PMID 27367711, 2016). "mIHC was performed on tumour specimens obtained from patients diagnosed with gastric and rectal cancer, aiming to investigate the association between the expression levels of LOX and LOXL2 and the presence of CAFs expressing α‐SMA, as well as TAMs expressing CD68 and CD206." (PMID 40179101, 2025). "In the LOX 473AA-positive population, females were more susceptible than males to carcinogenesis with OR values (female vs. male): 5.25 vs. 3.23, 2.29 vs. 1.51, 2.27 vs. 1.45, and 2.25 vs. 1.53, respectively, for lung, colon-rectum combined, colon, and rectum cancers." (PMID 27367711, 2016). "Our results showed that in gastric and rectal cancer specimens, tumour areas with high expression of LOX and LOXL2 also exhibited significant expression of α‐SMA, a specific surface marker for CAFs." (PMID 40179101, 2025). "Our data further show that high nuclear expression of LOX was positively correlated with poor survival in rectal cancer patients in multivariable analysis." (PMID 28947950, 2017). "In conclusion, this study demonstrated that LOX expression in the nucleus is a promising prognostic biomarker in rectal cancer patients." (PMID 28947950, 2017). "Since preoperative RT has been well established as a standard treatment in rectal cancer, we further evaluated the effect of RT on LOX expression and localisation." (PMID 28947950, 2017). "In this study, we analysed the LOX expression patterns in the nuclei of rectal cancer patient samples and determined the clinical significance of this expression." (PMID 28947950, 2017). "Our results show a powerful link between nuclear LOX expression in tumours and patient survival, and offer a promising prognostic biomarker for rectal cancer patients." (PMID 28947950, 2017). "We are the first to show LOX (50-kDa and 32-kDa isoform) expression in the nucleus of patient samples and in vitro in cancer cells and, more importantly, we identify it as an independent prognostic factor in rectal cancer patients." (PMID 28947950, 2017). "We also analysed whether RT affected the LOX expression and localisation in patient samples and cell lines since preoperative RT is the standard treatment for rectal cancer patients." (PMID 28947950, 2017). "In this study, we analysed LOX expression separately either in the cytoplasm, or in the nucleus, in a series of rectal cancer specimens from the patients participating in a randomized Swedish rectal cancer trial of preoperative radiotherapy (RT) with long-term follow up data." (PMID 28947950, 2017). "In the present study, our data showed that nuclear rather than cytoplasmic LOX protein expression in the primary rectal cancer was positively correlated with phospho-NF-κB p65 expression." (PMID 28947950, 2017). "Furthermore, for the first time, we showed by multivariable analysis that nuclear LOX, not cytoplasmic LOX, was a robust and independent prognostic factor in rectal cancer patients." (PMID 28947950, 2017).
Sepsis (3 papers, 2023). Sepsis is defined as life-threatening organ dysfunction caused by a dysregulated host response to infection. "Thus, restoring the balance among various EFAs and their metabolites, cytokines, desaturases, COX, and LOX enzymes is needed to suppress inappropriate inflammatory events in sepsis, in order to restore homeostasis." (PMID 37759732, 2023).
allergic disease (2 papers, 2021 to 2023). An immune response that occurs following re-exposure to an innocuous antigen, and that requires the presence of existing antibodies against that antigen. "Consequently, LOX inhibitors have been investigated as potential therapeutics for the treatment of inflammatory and allergic diseases." (PMID 37571024, 2023). "Besides, rhein significantly inhibited LOX enzyme activity, with IC50 value of 3.9 g/mL, suggesting that rhein can exhibit antiallergic activity by stabilizing or inhibiting LOX activity in mast cells, which indicates that rhein may be a potential therapeutic agent to treat allergic diseases." (PMID 34457021, 2021).
anovulation (2 papers, 2022 to 2024). The absence of ovulation. "Significantly increased FFA, LOX, and collagen abundance were observed in the ovaries of obese women with anovulation, compared to healthy controls or obese women with ovulation." (PMID 38333108, 2024). "Immunohistochemical staining revealed more intense LOX staining in ovarian granulosa cells and stroma in the obese women with anovulation than in either the control lean women or the obese women with ovulation." (PMID 38333108, 2024). "Notably, both FFA levels and LOX activity were significantly greater in the follicular fluid of the obese women with or without anovulation than in that of the control lean women but were greatest in the obese women with anovulation." (PMID 38333108, 2024).
arteriosclerosis (2 papers, 2016 to 2018). A vascular disorder characterized by thickening and hardening of the walls of the arteries. "On the other hand, LOX index reflects the initial stage of arteriosclerosis when other markers are still in the normal range." (PMID 28761986, 2018). "Interestingly, LOX index has been shown to reflect the progression of arteriosclerosis in the early stage, when other markers are still in the normal range." (PMID 28761986, 2018).
bronchogenic carcinoma (2 papers, 2021). A lung carcinoma arising from the bronchial epithelium. "As per the earlier study results, LOX is now widely accepted as poor prognostic factor, promoting cancer metastasis in breast, head and neck, lung, and bronchogenic carcinoma." (PMID 35054220, 2021).
cardiac interstitial fibrosis (2 papers, 2023 to 2024). "In aging hypertensive rats, MIT has also been shown to exert antifibrotic and -crosslinking properties by reducing cardiac interstitial fibrosis and LOX gene expression." (PMID 38337716, 2024). "After SAHA treatment, α-SMA intensity was reduced, as were cardiac interstitial fibrosis, and mRNA level of FN1 and LOX when compared with β2a-HFD-LN mice." (PMID 36763506, 2023).
cardiomyopathy (2 papers, 2022 to 2024). A disease of the heart muscle or myocardium proper. "However, further loss- or gain-of-function animal studies and human genetic studies are needed to validate the role of LOX in cardiac fibrosis and to determine whether LOX is a target for the treatment of cardiomyopathy." (PMID 35277059, 2022).